DDR1 (discoidin domain receptor tyrosine kinase 1)
Diseases named in the same sentence as DDR1 in open-access papers (continued):
Sharing a sentence is not in itself a finding about the gene and the disease.
chronic kidney disease (6 papers, 2016 to 2022). Impairment of the renal function secondary to chronic kidney damage persisting for three or more months. "Discoidin domain receptor 1 (DDR1), a receptor tyrosine kinase activated by collagen, contributes to chronic kidney disease." (PMID 34941574, 2022). "Functional roles of periostin and discoidin domain receptor 1 (DDR1) in experimental chronic kidney disease." (PMID 28536691, 2017). "Thus, targeting DDR1 can be a promising strategy in the treatment of chronic kidney disease." (PMID 26880216, 2016). "Recently, using a model of severe ischemia/reperfusion-induced acute kidney injury (AKI) that progresses to chronic kidney disease (CKD) and tubulointerstitial fibrosis, we showed by Western blot analysis that DDR1 is upregulated and activated both in the acute and chronic phases of kidney injury." (PMID 36249782, 2022).
glomerulonephritis (6 papers, 2016 to 2022). A renal disorder characterized by damage in the glomeruli. "Previous report indicated that the expression of Ddr1 gene is upregulated in glomerulonephritis, and the knockout of Ddr1 gene ameliorated renal pathology in a mouse model of glomerulonephritis." (PMID 33706638, 2021). "The present study includes results originally generated as part of a pharmaceutical program, aimed at the creation of a safe and effective DDR1 inhibitor to be used in patients affected by glomerulonephritis (GN)." (PMID 29859097, 2018). "In a mouse model of severe glomerulonephritis, both deletion and antisense treatment against DDR1 attenuated the renal damage." (PMID 28536691, 2017). "Most interestingly, inhibition of DDR1 with antisense oligonucleotides after establishment of the disease was protective in models of glomerulonephritis and ureteral obstruction." (PMID 28536691, 2017). "Moreover, AON-induced downregulation of DDR1, immediately after the initiation of the disease protects mice from the progression of glomerulonephritis." (PMID 36249782, 2022).
osteoarthritis (6 papers, 2019 to 2024). A noninflammatory degenerative joint disease occurring chiefly in older persons, characterized by degeneration of the articular cartilage, hypertrophy of bone at the margins and changes in the synovial membrane. "Ddr1-/- mice were recently found to spontaneously develop osteoarthritis of the temporomandibular joint, suggesting that loss of Ddr1 and associated increases in Ddr2 may initiate MMP-13 upregulation, resulting in type 2-collagen degradation." (PMID 32330138, 2020). "In osteoarthritis (OA) and rheumatoid arthritis (RA), where MMPs serve as important immune response factors as well, DDR1 is being explored as a potential therapeutic target." (PMID 39596178, 2024). "Our recent findings also revealed that the inhibition of DDR1 minimizes osteoarthritis through the autophagy mechanism." (PMID 37834343, 2023). "Collagenous-rich DDR1 triggers the ECM of cartilage to regenerate the cartilage tissue in osteoarthritis (OA) and temporomandibular disorder (TMD)." (PMID 37834343, 2023). "DDR1 and its regulation are observed in atherosclerosis, myxomatosis, rheumatoid arthritis, and osteoarthritis." (PMID 37834343, 2023). "With regards to the suitability of DDR1 as a therapeutic target, it is important to note that DDR1-null mice are viable, but these animals show glomerular defects and exhibit a high incidence of osteoarthritis." (PMID 31717573, 2019). "Understanding DDR1 signaling and its complex interactions in bone and cartilage may have implications for developing therapeutic approaches targeting musculoskeletal disorders, such as osteoporosis and osteoarthritis." (PMID 37834343, 2023). "DDR1 and DDR2 bind to collagen also to exert biological functions, like embryo development, ECM remodeling, organ fibrosis and osteoarthritis." (PMID 37122820, 2023).
osteosarcoma (6 papers, 2011 to 2024). A usually aggressive malignant bone-forming mesenchymal neoplasm, predominantly affecting adolescents and young adults. "While overexpression of DDR1 caused a significant increase of osteosarcoma cell motility and invasiveness." (PMID 39567474, 2024). "The IC50 (50% inhibition of DDR1 phosphorylation compared to control) of DDR1-IN-1 has been demonstrated to be sufficient to induce relevant changes in U2OS osteosarcoma human cell line." (PMID 32090682, 2020). "Moreover, as was observed in previous studies, the expression of DDR1 is increased in the osteosarcoma cell line U2OS after incubation with 2 μg/mL of doxycycline for 48 h." (PMID 36675255, 2023).
sarcoma (6 papers, 2015 to 2023). A usually aggressive malignant neoplasm of the soft tissue or bone. "Others have shown that DDR1 is one of the prominent molecules expressed by sarcomas characterized by constitutive IGF-2 overexpression." (PMID 28591735, 2017). "In particular, DDR1 is among the more prominent molecules expressed by sarcomas characterized by constitutive IGF-II overexpression." (PMID 25840417, 2015). "NSUN2 and NSUN7 were positively correlated with DDR1 expression in BLCA, HNSC, LIHC, sarcoma (SARC), THCA, and thymoma (THYM)." (PMID 37031216, 2023).
Alport syndrome (5 papers, 2016 to 2022). A rare renal disease characterized by glomerular nephropathy with hematuria progressing to end-stage renal disease (ESRD), frequently associated with sensorineural deafness, and occasionally with ocular anomalies. "The second study used a DNA-encoded library-derived DDR1 inhibitor in a mouse model of Alport syndrome." (PMID 36249782, 2022). "It is interesting to note that DDR1 genetic ablation in other models of chronic, acute or genetic renal disease, such as hypertensive nephropathy, Alport’s syndrome and unilateral ureteral obstruction, has been shown to be protective." (PMID 29859097, 2018). "Finally, western blot analysis revealed DDR1 upregulation in the mouse model of Alport syndrome." (PMID 36249782, 2022). "While the role of DDR1 in Alport syndrome has been studied, that of DDR2 is unknown." (PMID 33706638, 2021). "Thus, unlike DDR1, DDR2 might not be critically involved in the pathogenesis of Alport syndrome." (PMID 36249782, 2022).
idiopathic pulmonary fibrosis (5 papers, 2007 to 2023). Idiopathic pulmonary fibrosis (IPF) is a nonneoplastic pulmonary disease that is characterized by the formation of scar tissue within the lungs in the absence of any known cause. "DDR1 deletion was also found to be effective in reducing bleomycin-induced lung inflammation and pulmonary fibrosis." (PMID 34207360, 2021). "As it concerns the multifaceted mechanisms and factors involved in pulmonary fibrosis and neoplasia, an increased expression and activation of DDR1 have been reported." (PMID 27384677, 2016). "Although DDR1 has been previously discussed in the context of idiopathic pulmonary fibrosis and inflammation of the lung, a direct link with lung tumorigenesis has not yet been established." (PMID 17299390, 2007). "The compound has been suggested to reduce fibrosis because it either directly or together with an inhibitor of the main collagen receptor discoidin domain receptor 1 (DDR1) attenuated lung inflammation and fibroblast activation in idiopathic pulmonary fibrosis." (PMID 34070078, 2021). "Moreover, the upregulation of Discoidin domain receptor 1 (DDR1), a transmembrane collagen receptor, and EP300 was observed in samples from healthy or idiopathic pulmonary fibrosis (IPF) patients by single-cell RNA sequencing." (PMID 37569677, 2023). "In addition, it exhibited an inhibitory effect of DDR1-mediated signaling in a concentration dependent manner in PHLF (Primary Human Lung Fibroblast) and showed a blocking effect in BLM-induced lung fibrosis." (PMID 34207360, 2021).
pituitary adenoma (5 papers, 2012 to 2021). "The overexpressed DDR1 protein further increased the expression of MMP-2/9 which caused haemorrhagic/infarction of the pituitary adenoma." (PMID 29615979, 2018). "Down-regulated gene DDR1 was investigated that promoting pituitary adenoma cell proliferation and invasion by reason of increasing expression of DDR1 in hypoxia condition." (PMID 32192168, 2020). "Hypoxia is a positive regulator of DDR1 and DDR2 expression in nontumor cells, such as mesenchymal stem cells and smooth muscle cells, and in pituitary adenoma and breast tumor cells." (PMID 33917302, 2021).
serous ovarian cancer (5 papers, 2011 to 2022). "DDR1 overexpression was associated with advanced tumor stages in esophageal cancer, brain tumors and with poor survival, in lung adenocarcinoma and serous ovarian cancer." (PMID 35205677, 2022). "Consistent with studies of DDR1 in these solid tumors, elevated levels of DDR1 were seen in serous ovarian cancer in this study." (PMID 21541037, 2011). "The DDR1 protein was expressed in 63% (42/67) of serous ovarian cancer tissue, whereas it was undetectable in normal ovarian surface epithelium." (PMID 21541037, 2011). "Elevated DDR1 expression in serous ovarian cancer was also indicated as a prognostic determinant." (PMID 28143619, 2017). "The DDR1 protein was highly expressed in 69% (46/67) of serous ovarian cancer tissue samples." (PMID 21541037, 2011). "To characterize the expression of DDR1, we carried out immunohistochemical analysis of 67 primary serous ovarian cancers from patients who had not received any prior treatment, obtained from primary debulking surgery." (PMID 21541037, 2011).
skin cutaneous melanoma (5 papers, 2019 to 2023). "Although not statistically significant, the analysis of the different skin melanoma subtypes showed that DDR1 expression is always high for BRAF and NF1 mutants, while there are few outliers with low DDR1 expression for RAS mutants and triple wild-type samples." (PMID 33014862, 2020). "However, we found that DDR1 and BRAF are co-expressed in the majority of skin melanoma samples (80%) regardless of BRAF mutational status." (PMID 33014862, 2020).
Alzheimer disease (4 papers, 2017 to 2025). A progressive, neurodegenerative disease characterized by loss of function and death of nerve cells in several areas of the brain leading to loss of cognitive function such as memory and language. "Examples of DRL-based de novo drug design include the development of adenosine A2A receptor ligands, rapid identification of potent DDR1 kinase inhibitors, and the development of a large number of new BACE1 inhibitors, which is an enzyme involved in Alzheimer’s disease." (PMID 33562347, 2021).
Breast Invasive Carcinoma (4 papers, 2019 to 2025). "This compensatory mechanism has been previously reported in invasive breast carcinoma from patients in which DDR1 and DDR2 were coordinately and inversely deregulated." (PMID 31130862, 2019). "For example, while KM-Plotter and TIMER 2.0 both reported high DDR1 expression in invasive breast carcinoma (IBC, referred to as BRCA in TCGA), GEPIA 2.0 showed no significant upregulation compared to paired normal tissues." (PMID 40869052, 2025).
cervical cancer (4 papers, 2020 to 2024). A primary or metastatic malignant neoplasm involving the cervix. "Thus, our next work was devoted to finding the adapter protein that linked DDR1 and downstream signals in cervical cancer." (PMID 39567474, 2024). "Subsequently, we evaluated the in vivo metastatic potential of DDR1-expressing cervical cancer cells in the xenograft mouse model." (PMID 39567474, 2024). "This work sheds light on the mechanism by which DDR1 functions in cervical cancer cells, providing therapeutic strategy for the treatment of cervical cancer." (PMID 39567474, 2024). "In this study, we found that DDR1 was significantly more expressed in cervical cancer samples than in normal tissues." (PMID 39567474, 2024). "While DDR1 was increased in cervical cancer that was the outcome after analyzing data from GEO and GEPIA." (PMID 39567474, 2024). "In contrast, cervical cancer cells with reduced DDR1 expression exhibited a lower migration rate, fewer invasive cells, and decreased levels of EMT markers." (PMID 39567474, 2024). "SRY-Box transcription factor 2 (SOX2), a known oncogene in cervical cancer, showed a positive correlation with DDR1 and regulated DDR1 transcription, contributing to the elevated expression of DDR1 in cervical cancer." (PMID 39567474, 2024). "The increased DDR1 expression was also observed in cervical cancer clinical samples provided in this study." (PMID 39567474, 2024). "Nevertheless, the function and detailed mechanism of DDR1 in the development of cervical cancer remain obscure." (PMID 39567474, 2024). "Regarding the function of DDR1 in cervical cancer, the overexpression of DDR1 caused an increase in the migration, invasion, and epithelial-mesenchymal transition (EMT) of cervical cancer cells." (PMID 39567474, 2024). "In cervical cancer samples that we collected, the expression of DDR1 and SOX2 were increased, compared with paracancerous tissues." (PMID 39567474, 2024). "In vivo, mice injected with cervical cancer cells with overexpressed DDR1 showed more pulmonary metastasis and nodule number." (PMID 39567474, 2024). "DDR1 increased the phosphorylation of key proteins in cervical cancer cell." (PMID 39567474, 2024). "Therefore, NAT10 improves the stability of DDR1 mRNA by acetylation, promoting the growth, proliferation, invasion, and migration of cervical cancer cells." (PMID 38233930, 2024). "We study the adaptor protein of DDR1 in cervical cancer cell." (PMID 39567474, 2024). "In addition, the reduced migration rate and invasive cell number, and attenuated phosphorylation of 4EBP1 and EPHA2 supported that DDR1 influenced the migration and invasion of cervical cancer via GRB2." (PMID 39567474, 2024). "The migration, invasion, and EMT of cervical cancer cells were accelerated by DDR1 in vitro and in vivo, evidenced by increased migration rate and invasive cell number, changed EMT indexes, more cell metastasis and number of metastatic nodules, and bigger nodule size." (PMID 39567474, 2024). "Here, we sought to emphatically explore the function of DDR1 in cervical cancer." (PMID 39567474, 2024). "Opposite results were found in mice injected with DDR1 silenced cervical cancer cells." (PMID 39567474, 2024). "Thus, the function of DDR1 in cervical cancer was further assessed in this study." (PMID 39567474, 2024).
cervical cancer (continued). "We next asked whether DDR1 played a role through GRB2 in cervical cancer." (PMID 39567474, 2024). "However, whether GRB2 serves as an adaptor protein mediating the role of DDR1 in cervical cancer remains unknown." (PMID 39567474, 2024). "Furthermore, DDR1 bound directly with Src homology 2 domain of growth factor receptor bound protein 2 (GRB2) which mediated the function of DDR1 in the malignant behaviors of cervical cancer and the phosphorylation of downstream targets." (PMID 39567474, 2024). "It seemed to suggest that DDR1 was the downstream of SOX2, when SOX2 acted as an oncogene in cervical cancer." (PMID 39567474, 2024). "In summary, the present study suggests that DDR1 bound to the SH2 domain of GRB2, thereby affecting downstream phosphorylation signals and ultimately exacerbating the migration, invasion and EMT of cervical cancer cells." (PMID 39567474, 2024). "With the current results, we demonstrated that DDR1 was transcriptionally regulated by SOX2 and facilitated the transfer of cervical cancer cell." (PMID 39567474, 2024). "In conclusion, DDR1 binds directly to GRB2 and then affects downstream phosphorylation signals, ultimately exacerbating the metastasis of cervical cancer cells." (PMID 39567474, 2024). "In cervical cancer, NAT10 overexpression induces HNRNPUL1 and DDR1 mRNA expression by promoting acetylation, enhancing tumor proliferation, invasion, and metastasis." (PMID 38233930, 2024). "Firstly, increased DDR1 and SOX2 were verified in cervical cancer samples." (PMID 39567474, 2024). "Mechanistically, whether SOX2 had a regulatory effect on DDR1 transcription and whether GRB2 mediated DDR1 function in cervical cancer were explored." (PMID 39567474, 2024). "Thus, overall results showed that DDR1 enhanced the migration and EMT of cervical cancer cell." (PMID 39567474, 2024). "Furthermore, DDR1 was transcriptionally regulated by SOX2 and might be a probable biomarker in cervical cancers." (PMID 39567474, 2024).
chronic myeloid leukaemia (4 papers, 2018 to 2023). "Nilotinib tyrosine kinase inhibitor works potently against DDR1 and is used to treat adults with chronic myeloid leukemia." (PMID 33981329, 2021). "Consistent with this idea, pharmacological DDR1 inhibition with nilotinib, a TK inhibitor currently used in the clinic to target the BCR‐ABL oncogene in chronic myeloid leukaemia, displays a potent anti‐metastatic activity in CRC." (PMID 29438985, 2018).
Cirrhosis (4 papers, 2020 to 2024). A chronic disorder of the liver in which liver tissue becomes scarred and is partially replaced by regenerative nodules and fibrotic tissue resulting in loss of liver function. "In summary, DDR1 is induced in human cirrhosis, HCC, and ICC and inversely associated with the survival of HCC patients." (PMID 33173221, 2020). "This provides a mechanical insight, as well as a potential combination strategy by targeting DDR1 to enhance ICI response in HCC patients with cirrhosis." (PMID 38388466, 2024). "The synergic effect of targeting DDR1 with nilotinib and ICI with well tolerance is of appealing therapeutic value in HCC, especially those with advanced cirrhosis." (PMID 38388466, 2024). "Modulating cirrhotic-ECM by targeting DDR1 with nilotinib efficiently reverse NETs-dominant immune-suppressive TME, enhancing the aPD-1 treatment in HCC with cirrhosis, presenting an appealing therapeutic prospect." (PMID 38388466, 2024).
gastric tumor (4 papers, 2017 to 2025). "Array comparative genomic hybridization analysis showed DDR1 amplification in 50.96% of 104 gastric tumors and 58.06% of 27 gastric cell lines." (PMID 40456688, 2025). "In the in vivo drug efficacy study, the DDR1 inhibitor 7rh exhibited potent inhibitory effects on the growth of high DDR1-expressing gastric tumors even as a single agent." (PMID 40456688, 2025). "Gastric tumors develop fewer lymphatic vessels if DDR1 expression is inhibited and lymphatic endothelial cells are unable to form tubes when DDR1 expression is suppressed by siRNA or with miR199a/b-5p." (PMID 33917302, 2021). "Furthermore, selective DDR1 inhibitors were demonstrated to be capable of blocking the rapid growth of DDR1-positive gastric tumors in vivo." (PMID 40456688, 2025). "Overall, these results underscore DDR1's pivotal role in GC progression and suggest that gastric tumors with DDR1 overexpression may benefit from treatment with DDR1-selective inhibitors." (PMID 40456688, 2025).